HUNK (hormonally up-regulated Neu-associated kinase)
Tractability: Small molecule: a high-quality ligand is known; it belongs to a druggable protein family. Antibody: the Human Protein Atlas places it where antibodies can reach. PROTAC: ubiquitination databases record sites on it; a small molecule that binds it is known.
Target class: Kinase; Protein Kinase; Enzyme; CAMK protein kinase group
Gene: Protein-coding gene on chromosome 21 (31,873,020 to 32,044,633, forward strand). Ensembl gene ENSG00000142149.
Subcellular location (Human Protein Atlas): Nucleoplasm; Plasma membrane
Gene Ontology:
Molecular function: protein binding; protein serine/threonine kinase activity; ATP binding; protein kinase activity; protein serine kinase activity
Biological process: intracellular signal transduction; signal transduction
Cellular component: cytoplasm
Genetic constraint (gnomAD): Loss-of-function variants: 14 observed, 56.17 expected, observed/expected ratio (o/e) 0.25, 90% interval 0.16 to 0.39. The upper end of that interval is the gene's LOEUF score, 0.39, which puts it in group 1 of 6, group 1 being the genes least tolerant of losing a copy. Missense variants: 744 observed, 891.33 expected, observed/expected ratio (o/e) 0.83, 90% interval 0.79 to 0.89. Synonymous variants: 361 observed, 368 expected, observed/expected ratio (o/e) 0.98, 90% interval 0.9 to 1.07.
Homologues: Orthologues: chimpanzee HUNK (99% identical), macaque HUNK (99% identical), mouse Hunk (92% identical), pig HUNK (92% identical), rat Hunk (92% identical), dog HUNK (92% identical), guinea pig HUNK (83% identical), rabbit HUNK (82% identical), Drosophila melanogaster Nuak (22% identical), Drosophila melanogaster Snrk (17% identical), Caenorhabditis elegans ZK524.4 (17% identical), Caenorhabditis elegans C27D6.11 (15% identical), and 2 more. Paralogues in human: SIK3 (25% identical), SIK2 (23% identical), BRSK1 (22% identical), BRSK2 (22% identical), SIK1 (22% identical), NUAK2 (21% identical), NUAK1 (20% identical), MELK (20% identical), SNRK (19% identical), PRKAA1 (19% identical), PRKAA2 (19% identical), TSSK2 (16% identical), and 5 more.